PDGFRA (platelet derived growth factor receptor alpha)
Diseases named in the same sentence as PDGFRA in open-access papers (continued):
Sharing a sentence is not in itself a finding about the gene and the disease.
myeloproliferative neoplasm (24 papers, 2012 to 2025). A clonal hematopoietic stem cell disorder, characterized by proliferation in the bone marrow of one or more of the myeloid (i.e., granulocytic, erythroid, megakaryocytic, and mast cell) lineages. "The differential diagnosis for IHES includes primary HES associated with myeloproliferative neoplasms, such as those with genetic mutations in PDGFRA, PDGFRB, FGFR1, and JAK2." (PMID 39867100, 2024). "However, mast cells in systemic mastocytosis aberrantly display CD25, which is a diagnostic marker of neoplastic mast cells in systemic mastocytosis variants and in platelet-derived growth factor receptor alpha (PDGFRA)-associated myeloproliferative disorders." (PMID 26904159, 2016). "FIP1L1::PDGFRA fusion, one of the major oncogenic fusion genes of myeloproliferative disorders, is another example of JM dysfunction." (PMID 38071343, 2023). "The lymphoma associated oncogene NPM/ALK significantly altered the expression of 91phosphopeptides whilst the myeloproliferative disorder oncogenes BCR/ABL, TEL/PDGFRβ, Kit D816V, and Fip1L/PDGFRα changed the expression of 94, 114, 111 and 68 respectively." (PMID 22745689, 2012). "Molecular cytogenetic analysis (FISH) for PDGFRA, PDGFRB, and FIP1L1 rearrangements returned negative, effectively ruling out an underlying myeloproliferative neoplasm." (PMID 40943043, 2025). "Genetic testing excluded acute myeloid leukemia, myeloproliferative neoplasms, myelodysplastic syndromes, systemic mastocytosis, and myeloid/lymphoid neoplasms with eosinophilia, as results for PDGFRA, PDGFRB, FGFR1, or PCM1-JAK2 rearrangements were negative." (PMID 39867100, 2024). "Tests for myeloproliferative neoplasm-related genes, such as JAK2 V617F and PDGFRα, were negative, and secondary causes such as parasitic infections, asthma, and allergies were excluded." (PMID 39703993, 2024). "On fluorescent in-situ hybridization (FISH), myeloproliferative neoplasms (MPN) testing was negative for platelet-derived growth factor receptor-alpha (PDGFRA), platelet-derived growth factor receptor-beta (PDGFRB), and fibroblast growth factor receptor-1 (FGFR1) rearrangement." (PMID 32656011, 2020).
acute myeloid leukemia (22 papers, 2012 to 2025). Acute myeloid leukemia (AML) is a group of neoplasms arising from precursor cells committed to the myeloid cell-line differentiation. "Fusion gene testing was completed in five patients, with cases 4 and 5 demonstrating FIP1L1::PDGFRA fusion gene positivity, and case 6 with TLS::ERG(+)acute myeloid leukemia." (PMID 41145290, 2025).
brain tumors (22 papers, 2012 to 2025). "Dose-response analyses demonstrated that both rPDGF-BB and rEndocan induced PDGFRa phosphorylation in brain tumor cells at low nanomolar concentrations." (PMID 39773984, 2025). "On the other hand, PDGF-A;P2 (hereafter called “P3”) mice when fed a DOX diet developed brain tumors that expressed human PDGFRα." (PMID 30082792, 2018). "Since gB can act as a PDGFRα ligand, and signaling via this receptor tyrosine kinase drives a subset of human glioblastomas, we sought to investigate the specific pathways impacted by HCMV gB signaling via PDGFRα in human brain tumors." (PMID 24658280, 2014). "PDGFRA is a receptor tyrosine kinase (RTK) and is one of the commonly mutated oncogenes that drive tumor growth in glioblastoma, the most aggressive and lethal brain tumor." (PMID 38634484, 2024). "Interestingly, a mouse model with a combination of CDKN2A−/− and a PDGFRA point mutation showed brain tumors with double minute chromosomes or ecDNA40, while another CDKN2A−/− mouse model that generated brain tumors after irradiation similarly had ecDNA41." (PMID 31992716, 2020). "The enhanced effect of the combination of regorafenib with DNA damaging agents may depend on the PDGFRA amplification in these two brain tumor models." (PMID 26599335, 2015). "Besides brain tumors, most animals also developed aggressive fibrosarcomas, likely triggered by Cre activation of mutant PDGFRα in fibroblastic cell lineages." (PMID 25683249, 2015). "The data taken as a whole indicates that OKN-007 may possibly be an effective anti-cancer agent for some patients with pHGGs by inhibiting cell proliferation and angiogenesis, potentially via the PDGFRα pathway, and could be considered as an additional therapy for pediatric brain tumor patients." (PMID 26248280, 2015). "Furthermore, OPCs isolated from mutants proliferated at a normal rate in vitro and mutant cohorts developed no signs of brain tumors, indicating that PDGFRα J/K mutation by itself is insufficient to increase OPC proliferation or drive gliomagenesis." (PMID 25683249, 2015). "This study indicates that OKN-007 may be an effective anti-cancer agent for some patients with pGBMs by inhibiting cell proliferation and angiogenesis, possibly via the PDGFRα pathway, and could be considered as an additional therapy for pediatric brain tumor patients." (PMID 26248280, 2015). "The methylation profile confirmed the diagnosis of both brain tumors and PDX, refining the classification of dpHGG, Rtk1 subtype, subclass A, with an actionable alteration on Platelet‐derived growth factor receptor A (PDGFRA)." (PMID 40880425, 2025). "To investigate the composition of NHERF1 protein complexes in ependymoma, we screened the intracellular localization of the NHERF1 ligands moesin, NF2, PTEN, PDGFRα, EGFR, YAP1, β-catenin and PHLPP2 that have been functionally involved in primary brain tumors." (PMID 25775275, 2015). "While FGFR1 was overexpressed in a variety of nonhematopoietic tumor types, PDGFRA was exclusively overexpressed in brain tumors, and FLT3 was exclusively overexpressed in acute leukemias." (PMID 31651965, 2019). "Our study shows that in the absence of autophagy, PDGFRA-driven brain tumor formation is inhibited." (PMID 38634484, 2024).
colorectal cancer (22 papers, 2012 to 2025). A primary or metastatic malignant neoplasm that affects the colon or rectum. "PDGFRA mutations are reported in human cancers including colorectal cancer (6.0%) and stomach cancer (2.6%) in the public data of COSMIC v71." (PMID 26475379, 2015). "Notably, the presence of the PDGFRA gene, associated with tumour angiogenesis, hints at the viability of targeting angiogenesis as a potential treatment strategy for colorectal cancer." (PMID 39120548, 2024). "The Cancer Cell Line Encyclopedia (CCLE) data indicate that sorafenib targeting PDGFRA only had a potential drug response in colorectal cancer." (PMID 34702313, 2021). "Only cytoplasmic stain was found by Wehler and al using the same anti-PDGFRα antibody in all colorectal cancer samples studied." (PMID 33213472, 2020). "Thus, the study of multiple regions of CMS4 colorectal cancers and the analysis of PDGFRA, PDGFRB, PDGFC and KIT showed the existence of a consistent intratumor heterogeneity." (PMID 29652830, 2018). "Immunohistochemical analysis (CACNA1G-N) of cross sectioned tissues showed CACNA1G protein localized in PDGFRα+/β+ cells at low level in healthy colon, but the protein was increased in PDGFRα+/β+ cells within the hypertrophied smooth muscle of colorectal cancer." (PMID 28806761, 2017). "Therefore, FDA-approved drugs targeting PDGFRA, such as regorafenib for colorectal carcinoma and pazopanib for renal carcinoma, may inhibit tumor progression of PPC with high PDGFRA expression." (PMID 34158601, 2021). "As a result, our findings suggest that PDGFRα may have an effect on colorectal cancer prognosis." (PMID 33213472, 2020). "To confirm the existence of CAFs with specific signatures, we applied immunofluorescence analysis and we detected the expression of PDGFRA (iCAFs marker) and RGS5 (mCAFs marker) in colorectal cancer." (PMID 35794563, 2022). "The drug regorafenib is approved for late stage colorectal cancer patients; regorafenib inhibits RAF-1, B-RAF as well as PDGFRα/β." (PMID 29245915, 2017). "In agreement with the Western blot data, CACNA1G was increased within PDGFRα+/β+ cells and SMC in the hypertrophied smooth muscle of colorectal cancer." (PMID 28806761, 2017). "When compared with suspected Tr-CAFs in other types of cancer, the high level of PDGFRa was a common feature; however, most other known markers, including Meflin, were not significantly expressed in Tr-CAF of colorectal cancer." (PMID 40759242, 2025).
osteosarcoma (22 papers, 2014 to 2025). A usually aggressive malignant bone-forming mesenchymal neoplasm, predominantly affecting adolescents and young adults. "Evidence suggests that low expression of the E3 ubiquitin ligase c-CBL protein is closely associated with high expression levels of epidermal growth factor receptor (EGFR) and platelet-derived growth factor receptor alpha (PDGFRα) in osteosarcoma tissues." (PMID 39062505, 2024). "Fifteen cases of primary osteosarcoma were analyzed for established markers associated with CAR cells (LEPR, EBF3, CXCL12, PDGFRA) and subdivided into low‐grade parosteal (7/16) or high‐grade intramedullary (9/16) tumors." (PMID 35309866, 2022). "Our data revealed that among the decreased phosphorylated receptors, PDGFRα appears as the most sensitive target of imatinib mesylate in osteosarcoma." (PMID 24599309, 2014). "Furthermore, genomic sequencing of 71 paediatric and adult osteosarcoma samples reported 20% had an amplification at 4q12 spanning PDGFRA, VEGFR2, and KIT, and in total, 40% of participants had either PDGFRA or VEGF amplification." (PMID 40983796, 2025). "Similarly, amplifications of MYC, BRCA2, and a co‐amplification of the region PDGFRA–KIT occurred mostly in recurring tumors (P1, P2, P4, P6, P7, P10), whereas JUN and APC mutations occurred in a single osteosarcoma primary (P1)." (PMID 33963544, 2021). "We indeed previously reported that metastatic and recurrent osteosarcoma tumors expressed higher EGFR and PDGFRα levels than localized tumors." (PMID 30642298, 2019). "However, clinical trials in osteosarcoma have shown that single‐target therapy, such as inhibiting VEGFs (with bevacizumab), KIT and PDGFRα (with imatinib), or IGF‐1R (with cixutumumab or R1507) has limited efficacy." (PMID 40344484, 2025). "Here, we analyze osteosarcomas via immunohistochemistry for known markers of CAR cells such as leptin receptor (LEPR), B‐cell factor 3 (EBF3), CXCL12, and platelet‐derived growth factor receptor alpha (PDGFRA)." (PMID 35309866, 2022). "Furthermore, we showed that TAS‐115 inhibited the phosphorylation of PDGFRα, AXL, and FLT‐3 and decreased cell proliferation in LM8 and other human osteosarcoma cell lines." (PMID 32128992, 2020). "However, clinical trials in osteosarcoma have demonstrated the low efficacy of single-target therapy by inhibiting VEGFs (by bevacizumab), KIT and PDGFRα (by imatinib), and IGF-1R (by cixutumumab or R1507)." (PMID 32984034, 2020). "Overall and disease-free survival analysis did not reveal any differences between osteosarcoma patients, according to the level of PDGFRA expression." (PMID 30083310, 2018). "PDGFRA alterations have not been reported in any of the 54 osteosarcoma cases analyzed (COSMIC, Nov 2014)." (PMID 26510912, 2015). "Furthermore, BF (from osteosarcoma) and BI (from GIST), also resistant to Zalypsis, showed low PDGFRα levels but high levels of c-Kit." (PMID 24758355, 2014). "Finally, PDGFRα, Axl, PDGFRβ, RYK, EGFR, EphA2, EphA10 and IGF1-R are key targets of imatinib mesylate in osteosarcoma." (PMID 24599309, 2014). "For example, the combination of Olaratumab, a monoclonal antibody against platelet-derived growth factor receptor alpha, with doxorubicin provided no detectable clinical benefit in terms of PFS and overall survival in osteosarcoma compared to conventional chemotherapy." (PMID 37681936, 2023).
chronic myeloid leukemia (21 papers, 2013 to 2026). "Imatinib mesylate is a tyrosine kinase inhibitor that was originally designed to inhibit the BCR-ABL tyrosine kinase in chronic myeloid leukemia, but was also found to inhibit other related receptors, such as PDGFRα." (PMID 35528149, 2022). "Dasatinib is an orally available TKI of ABL1, SRC family kinases, KIT, and PDGFRα/β, and has been approved for the treatment of chronic myeloid leukemia (CML) and Philadelphia-chromosome-positive acute lymphoblastic leukemia (Ph+ ALL)." (PMID 34207383, 2021). "Indeed, imatinib, a well-known anticancer drug for chronic myeloid leukemia, has also been shown to inhibit the iCAFs marker PDGFRA to suppress angiogenesis in cervical carcinoma." (PMID 38182557, 2024). "It was speculated that imatinib, a platelet-derived growth factor receptor alpha inhibitor used for chronic myeloid leukemia, was involved." (PMID 36271412, 2022). "Imatinib has indeed changed the fate of patients with GIST and Philadelphia chromosome-positive chronic myeloid leukemia by targeting the oncogenic drivers of these diseases—BCR–ABL1 and KIT and/or PDGFRA—mutations that promote the function of tyrosine kinase activities." (PMID 33552970, 2020). "Imatinib is a very potent inhibitor of tyrosine kinases such as ABL kinase, chimeric oncoprotein BCR-ABL of chronic myeloid leukemia, transmembrane KIT receptors, PDGFRα, and PDGFRb." (PMID 37623504, 2023). "Imatinib is an inhibitor of kinases such as the PDGFRA and PDGFRB receptors, currently used to treat some cancers such as chronic myeloid leukemia or gastrointestinal tumors." (PMID 34975915, 2021). "Imatinib mesylate (Gleevec, STI571), an inhibitor of ABL, PDGFRα, and KIT tyrosine kinases, is successfully applied to the treatment of BCR-ABL-positive chronic myelogenous leukemia (CML)." (PMID 25431951, 2014).
liver fibrosis (21 papers, 2014 to 2025). "We investigated the role of PDGFRα in liver fibrosis using mice with only one allele of Pdgfrα, and found that reducing Pdgfrα copy number inhibits liver fibrosis in mice." (PMID 24667490, 2014). "The experimental and clinical evidence indicate that PDGFRα is implicated in liver fibrosis." (PMID 39599900, 2024). "Elevated expression of PDGFRs is associated with liver fibrosis and cirrhosis, so we sought to determine whether PDGFRα regulates liver fibrogenesis using mice that have one allele of Pdgfrα (PdgfrαWT/nGFP)." (PMID 24667490, 2014). "In liver fibrosis, both PDGFRα and PDGFRβ are upregulated, with PDGFRα expressed in liver progenitor cells and PDGFRβ mainly expressed in HSCs." (PMID 40393967, 2025). "Recent studies demonstrated that mice deficient in PDGFRα specifically within HSCs or hepatocytes exhibited diminished fibrosis in model mice with drug-induced liver injury, suggesting the involvement of PDGFRα signaling in hepatic fibrosis." (PMID 39394459, 2024). "HSC-derived EVs contain connective tissue growth factor (CTGF) and are enriched in platelet-derived growth factor receptor-α (PDGFRα), and thus promote the progress of liver fibrosis." (PMID 39599900, 2024). "Beyond hepatocytes, HSCs have also been reported to release platelet-derived growth factor receptor alpha (PDGFRα) and glycolysis-related protein-enriched EVs that promote hepatic fibrosis." (PMID 39767572, 2024). "Patients with liver fibrosis had significantly higher PDGFRα levels in serum EVs compared to healthy controls." (PMID 39599900, 2024). "The EVs promoted migration in recipient HSC and liver fibrosis in healthy mice, while inhibiting EV export of PDGFRα ameliorated fibrosis in carbon tetrachloride (CCL4)-treated mice." (PMID 35397694, 2022). "PDGFRα levels were enhanced in serum EVs from ALD patients with hepatic fibrosis or mice with CCl4 or BDL hepatic fibrosis." (PMID 34202136, 2021). "It has been reported that PDGFRα+ progenitor cells give rise to major matrix-producing Fbs in tendon repair, liver fibrosis, and kidney and heart ischemic injury." (PMID 34335301, 2021). "We report for the first time that conditional abolition of PDGFRα expression in hepatocytes attenuates chemically induced liver fibrosis by suppressing the upregulation of PDGFRα and TGFβ in HSCs, reducing their activation and proliferation." (PMID 30509307, 2018). "The proliferation of PDGFRα-positive HSCs during liver fibrosis can be suppressed by blocking of PDGFRα in HSCs." (PMID 30509307, 2018). "PDGFRα participates in liver fibrosis, as evidenced by increased PDGFRα expression in cirrhotic human livers, human cell lines, and a mouse model of liver fibrosis." (PMID 30509307, 2018). "This suggests that in the event of chronic liver injury, PDGFRα in hepatocytes plays an important role in liver fibrosis by affecting PDGFRα expression in HSCs." (PMID 30509307, 2018). "Normal adult hepatocytes express a low level of PDGFRα, the role of which in hepatocytes in liver fibrosis was unclear." (PMID 30509307, 2018). "To address the role of hepatocyte PDGFRα in liver fibrosis, we generated hepatocyte-specific conditional PDGFRα KO mice." (PMID 30509307, 2018). "Our findings suggest that although PDGFRα expression in normal hepatocytes is negligible, it is upregulated by liver insult and plays a vital role in liver fibrosis by facilitating the activation and proliferation of HSCs." (PMID 30509307, 2018). "PDGFRα expression is markedly elevated in chronic liver injury and enhanced PDGFRα activation contributes to liver fibrosis." (PMID 30509307, 2018). "Conditional PDGFRα KO mice had attenuated TAA-induced liver fibrosis with decreased HSC activation and proliferation." (PMID 30509307, 2018). "A recent study also demonstrated that reducing PDGFRα signaling in heterozygous PDGFRα mice showed alleviation of liver fibrosis from CCl4 injury." (PMID 28465473, 2017).